RB1 (RB transcriptional corepressor 1)
Diseases named in the same sentence as RB1 in open-access papers (continued):
Sharing a sentence is not in itself a finding about the gene and the disease.
retinoblastoma (continued). "In contrast to human ocular biology, loss of Rb1 is not sufficient to generate retinoblastomas in mice, and thus, similar underlying genetic differences may explain why loss of Dicer1 functions have not yet been associated with IO-MEPL-like lesions in previous mouse studies." (PMID 34785636, 2021). "Retinoma or retinocytoma could cause leukocoria and accounts for 3% of pseudo retinoblastomas has redefined as a precancerous lesion characterized by the loss of function of both copies of the RB1 gene, but lacking the additional genomic changes characteristic of retinoblastoma." (PMID 34815392, 2021). "We verified that HELLS overexpression occurs soon after tumor initiation in Chx10-Cre Rb1lox/lox p107−/− (Rb1/p107 DKO) retinae and this overexpression persists in retinoblastoma tumors." (PMID 32071286, 2020). "In addition, the exclusion of 3 RB1 variant carriers with no diagnosis of retinoblastoma could have affected data." (PMID 33090227, 2020). "Searches can find exact matches to UniProt accessions (e.g. ‘P06400’), protein or gene names (‘Retinoblastoma’ or ‘RB1’) and any common synonyms (‘pRB’, ‘pp110’)." (PMID 32507889, 2020). "Deletion of the 13p region, including the RB1 locus, is known in a subset of LMS, and LMS arising in the setting of hereditary retinoblastoma has been described." (PMID 30804704, 2019). "While germline RB1 mutations can be isolated from the peripheral blood and used to stratify the risk of second ocular and non-ocular tumors for patients with heritable disease, this has little to no impact on the diagnosis of retinoblastoma, nor on the prognostication for globe salvage." (PMID 31835688, 2019). "We have previously found high expression of the ligand Nodal at the mRNA and protein levels in multiple retinoblastoma lines, including Y79 and WERI Rb1." (PMID 31451106, 2019). "The proliferative role of CDK/cyclin proteins, in general, is mediated through the phosphorylation of the major CDK‐substrate, RB1 (Retinoblastoma) tumor suppressor, and its related proteins RBL1 (p107) and RBL2 (p130) [collectively referred to here as pRB]." (PMID 31566717, 2019). "In human embryonic stem cells, knocking out RB1 gene by CRISPR/Cas9 would lead to the formation of neural enriched teratomas, which mimic the trilateral retinoblastoma tumors." (PMID 30109230, 2018). "For this rb1, rbl1 and a modifier are targeted by triple multiplex CRISPR/Cas9 and retinoblastomas should be (micro)dissected." (PMID 27739525, 2016). "We show rapid and penetrant retinoblastoma development in X. tropicalis, by co-targeting of rb1 and rbl1 with multiplex CRISPR/Cas9, closely recapitulating the histopathological hallmarks of clinical retinoblastoma." (PMID 27739525, 2016). "In parallel we observed by CCK-8 assay that cell growth was reduced from 60 to 90% in WERI Rb1 and from 75 to 95% in Y79, upon suppression of PI3KC2β, as compared to scrambled shRNA, implying that PI3KC2β might play an important role in regulating retinoblastoma growth and survival." (PMID 27661116, 2016). "High-risk alpha E7 represses the retinoblastoma family of tumor suppressors: RB1 (retinoblastoma), RBL1 (p107), and RBL2 (p130); E7 targets the degradation of RB1, which is tied to the cancer phenotype." (PMID 26470018, 2015). "Nevertheless, we should focus on novel therapeutic approaches targeting to other molecular aberrations which might have roles in the progression of retinoblastoma, because Rb1 mutation is not a sufficient condition for the malignant characteristics of retinoblastoma cells." (PMID 25359779, 2014). "It is important to emphasize that in our cohort of 10 retinoblastomas that we analyzed by WGS, FISH and IHC there were 5 tumors that had at least 1 intact RB1 gene (SJRB011, SJRB016, SJRB020, SJRB032, SJRB035)." (PMID 24509483, 2014). "To further assess the function of miR-24 in RB1-/- retinoblastoma cell lines, we transiently transfected WERI-Rb1 cells with a small interfering RNA (siRNA) against miR-24." (PMID 22336108, 2012).
retinoblastoma (continued). "RB1 LOH occurs at a frequency of 72.2% in basal-like breast tumours and 61.5% in luminal B tumours, both of which are observed in retinoblastomas in the frequency range of 60 to 75%." (PMID 18782450, 2008). "While 98% of non-heritable retinoblastomas have RB1 mutations, 2% have somatic amplification of the MYCN oncogene without a detectable RB1 mutation." (PMID 41009976, 2025). "An additional four patients diagnosed with retinoblastoma between December 2022 and July 2023, without germline RB1 findings, were included in this analysis." (PMID 38803632, 2024). "When the retinoblastoma tumor suppressor Rb1/Rbl1 is absent in the retina, the development of retinoblastoma is inhibited." (PMID 38955924, 2024). "The similarities and differences in the phenotype between the modelled variants are consistent with that seen in patients with MYCNA retinoblastomas regardless of RB1 status." (PMID 37606819, 2024). "Since the discovery of RB1 decades ago, numerous studies on retinoblastoma and related non-ocular tumors have shed light on the molecular and genetic role of RB1 in cancer development and inheritance." (PMID 38672640, 2024). "A small percentage of non-hereditary retinoblastomas are caused by MYCN amplification and normal RB1." (PMID 38920989, 2024). "Apart from the previously reported very young age of diagnosis for RB1-proficient retinoblastoma, we did not observe differences in gene expression, chromosomal or genetic features between the RB1−/− and RB1-proficient MYCN-amplified retinoblastomas." (PMID 39079981, 2024). "This patient’s bilateral retinoblastomas appears to result from the inactivation of the RB1 locus on der(X) in ~3% of her cells (an extension of local X-chromosome inactivation), that results in the heterozygous LOF of RB1 (MIM 614041)." (PMID 37808736, 2023). "Recent findings regarding other types of pediatric tumors such as retinoblastoma have shown that inactivation of the RB1 checkpoint is not per se necessary for the progression of cancer." (PMID 36982482, 2023). "A small percentage of retinoblastomas that are not inherited (less than 2%) are initiated by MYCN-amplification without RB1 inactivation." (PMID 37777551, 2023). "The present study dove deeper into the biology of the MYCN retinoblastoma subtype by correlating information of different molecular levels, defining MYCN-amplified RB1-proficient retinoblastoma as a unique retinoblastoma subtype with a distinct molecular background." (PMID 36245757, 2022). "Modelling retinoblastoma metastasis in vivo is complicated as RB1 inactivation alone is not sufficient to induce retinoblastoma in mice." (PMID 36497295, 2022). "About 1–2% of patients with retinoblastoma show no RB1 alteration but instead amplification of MYCN." (PMID 35565295, 2022). "We sought to assess the use of long‐read nanopore sequencing to rapidly characterise an apparent heterozygous RB1 exon 23 deletion that was initially identified by multiplex ligation‐dependent probe amplification (MLPA), in a patient with bilateral retinoblastoma." (PMID 35014072, 2022). "RB1, STAT3, and CDKN2A are the most likely core targets of curcumin for retinoblastoma treatment." (PMID 35911143, 2022). "Retinoblastoma (RB) is an aggressive intraocular malignancy of childhood initiated by biallelic inactivation of the RB1 gene, and a small subset (1–2%) develops with MYCN amplification in the presence of functional RB1." (PMID 36077715, 2022). "The majority of series investigating next-generation sequencing (NGS) in retinoblastoma have used this technology for germline RB1 detection, and copy number alteration details are not consistently available." (PMID 33466343, 2021). "A minority of non-hereditary retinoblastomas (<2%) are initiated by MYCN-amplification without RB1 inactivation." (PMID 34552068, 2021).
retinoblastoma (continued). "The lack of RB1 alterations in two samples is consistent with either RB1 negative tumorigenesis of retinoblastoma or a mechanism of RB1 inactivation not detectable by the methods used in this paper." (PMID 33466343, 2021). "Studies suggest that biallelic RB1 inactivation leads to a non-proliferative retinoma, and progression to retinoblastoma requires additional genetic aberrations." (PMID 34815392, 2021). "Patients with heritable retinoblastoma have a higher risk of extraocular malignancies (second primary malignancies, SPM) later in life compared to children without constitutional RB1 variant." (PMID 33807189, 2021). "Besides RB1, there is another gene, MYCN, which is the most commonly amplified gene found in retinoblastoma." (PMID 34639028, 2021). "Since the discovery and cloning of this gene decades ago, numerous studies of retinoblastoma and related non-ocular tumors have elucidated the molecular and genetic role of RB1 in cancer development and inheritance." (PMID 31683923, 2019). "Similarly, knocking out of Rb1 and Retinoblastoma-like 1 (Rbl1) genes by CRISPR/Cas9 led to retinoblastoma formation in Xenopus tropicalis." (PMID 30109230, 2018). "In light of the known genetic determinants and etiology of retinoblastoma, it is suspected that exogenous exposures may be important for both the unilateral and bilateral subtypes, however, more so for the unilateral as these children do not have inherited germline mutations in RB1." (PMID 29533992, 2018). "Considering the difference in phenotype between RB1+/+ and RB1+/+MYCNA genotypes, it is possible that it may be a question of different tumors combined under the name “retinoblastoma”." (PMID 29124525, 2017). "The murine retinoblastoma models have other genetic alterations in addition to Rb1 inactivation, however, these genetic modifications do not cause any distinguishable DNA methylation changes compared with wild-type retinae (data not shown)." (PMID 28467809, 2017). "These patients with unilateral RB1+/+MYCNA retinoblastomas are usually diagnosed at a younger age (mean age = 4.5 months) with distinct histological features and harbour fewer genomic copy-number changes characteristic of retinoblastoma." (PMID 28575107, 2017). "RB1-null human embryonic stem cells, generated using CRISPR/Cas9, were shown to form large teratomas with characteristics similar to trilateral retinoblastoma tumors and were proposed as a platform for studying mitochondrial phenotyping, in vivo tumorigenesis, and drug screening." (PMID 29124525, 2017). "A study in mice indicates that there is a limited time window during development where retinoblastoma can develop, and that in adult 3-week-old mice few retinoblastomas emerged when MYCN was overexpressed in retinas lacking RB1." (PMID 29124525, 2017). "Rb1 mosaics were raised up to sixteen months of age and none (n = 13) developed retinoblastoma distinguishable by gross examination." (PMID 27739525, 2016). "We have recently shown that retinoblastoma RB1 -/- cells cannot survive in the absence of MED4, both in vitro and in orthotopic xenograft models in vivo, therefore identifying MED4 as a survival gene in retinoblastoma." (PMID 26925970, 2016). "Murine retinoblastoma was first observed in chimeric animals lacking both Rb1 and Retinoblastoma-like 1 (Rb1/Rbl1), however the low recovery of viable chimeras precluded the generation of study-sized populations of retinoblastoma-bearing mice." (PMID 27739525, 2016). "As we did not detect any retinoblastoma after inactivation of either rb1 or rbl1, we next performed multiplex genome editing by co-injections of two independent pairs of rb1 and rbl1 gRNAs." (PMID 27739525, 2016). "Retinoblastoma failed to develop in mice in which Brg1 was conditionally inactivated, but when Brg1 inactivation was combined with biallelic inactivation of Rb1 and p107 tumorigenesis was accelerated compared with biallelic inactivation alone." (PMID 26628093, 2015).
retinoblastoma (continued). "Y79 cells, one of the most widely utilized retinoblastoma cell lines, are also known to be negative for RB1 gene." (PMID 25359779, 2014). "In addition to the previously reported recurrent focal losses of RB1 and BCOR and amplification of MYCN, we also identified a recurrent focal amplification of OTX2 in 3% of retinoblastomas." (PMID 24509483, 2014). "In addition to recurrent deletions in RB1, the most common focal deletions were in BCOR in 4% (4/94) of our retinoblastomas." (PMID 24509483, 2014). "Most cases of unilateral retinoblastoma involve somatic nonhereditary retinoblastoma 1 gene (RB1) mutations, which account for 60% of all retinoblastoma cases." (PMID 22876131, 2012). "Rb1 heterozygous mice also do not develop retinoblastomas, whereas most humans with the homologous genotype will have bilateral retinoblastomas either congenitally or during infancy." (PMID 21403899, 2011). "As such, genetic testing should be recommended to all patients with retinoblastoma, especially when the RB1 status is unknown, irrespective of tumor laterality, age at diagnosis, or family history." (PMID 41009976, 2025). "A rare form of RB was first reported in 2013, in which high-level amplification of the oncogene MYCN drives tumorigenesis in the absence of pathogenic RB1 mutations (MYCN-amplified, RB1+/+ retinoblastoma)." (PMID 41465072, 2025). "However, a small subset of cases, accounting for approximately 1.5% of all retinoblastomas, is characterized by high-level amplification of the MYCN oncogene without accompanying RB1 mutations." (PMID 40943594, 2025). "To identify therapeutic vulnerabilities specific to MYCN-driven retinoblastoma, we assessed drug sensitivity profiles of MYCN-overexpressing cells (MYCNO/E-cells) derived from retinal organoids compared with the established retinoblastoma cell line Y79 (RB1−/−, MYCN-amplified)." (PMID 40943594, 2025). "The retinoblastoma (RB) transcriptional corepressor 1 (RB1) stands as the first human tumor suppressor gene described by Dr. Alfred G. Knudson, who reported his observations on 48 cases of retinoblastoma, a rare eye cancer primarily affecting children, and associated reports." (PMID 38672640, 2024). "However, cells without RB1 had significantly higher flexibility to use glutamine or fatty acids, suggesting that Rb tumors use these alternate fuels for their growth." (PMID 36291051, 2022). "In the developing murine retina, conditional inactivation of both copies of Rb1 could not induce retinoblastoma." (PMID 36359825, 2022). "In fact, the downregulation of cell cycle G1 to S-phase transition genes such as cyclin kinase inhibitors may promote further proliferation, rather than inhibition, in MYCN-amplified RB1-proficient retinoblastoma." (PMID 36245757, 2022). "Thus, homozygous knockout of Rb1 in mice is lethal in the embryo and heterozygous animals frequently develop pituitary tumors, but not retinoblastoma." (PMID 35565295, 2022). "For patients possessing heritable retinoblastoma, at least one copy of the tumor initiating RB1 mutations could also be found in other non-cancerous cells, which could lead to lower RB protein levels and higher MMEJ efficiency in these cells." (PMID 34639028, 2021). "Furthermore, ~2% of retinoblastomas do not harbour RB1 alterations, and the presence of genetic alterations beyond RB1 inactivation correlates with aggressive histopathologic features." (PMID 34815392, 2021). "In addition, inactivation of one copy of Rb1 does not lead to the development of murine retinoblastoma at a detectable frequency." (PMID 34003213, 2021). "There was no somatic RB1 mutation identified in either the AH or the tumor for any of these cases; on histopathologic review, none of these eyes had characteristic features of primary MYCN amplified retinoblastoma tumors." (PMID 34283049, 2021).
retinoblastoma (continued). "Additionally, genome sequencing of retinoblastoma tumors without a previously identified RB1 alteration revealed large structural rearrangements encompassing the RB1 locus with variable complexity." (PMID 33827698, 2021). "However, the depletion of RB1 was not sufficient for retinoblastoma initiation as the organoids did not fully recapitulate the retinoblastoma cell phenotype." (PMID 33718380, 2021). "An uncommon subgroup of unilateral retinoblastomas with highly aggressive histological features, lacking aberrations in RB1 gene with high-level amplification of MYCN (MCYNamplRB1+/+) has only been described as intra-ocular cases treated with initial enucleation." (PMID 32971811, 2020). "In 1986, it was also shown that retinoblastoma tumor formation was not necessarily dependent on the oncogene MYCN, which was commonly amplified and highly expressed in retinoblastomas (as in neuroblastoma) that had lost RB1, likely contributing to tumor progression but not initiation." (PMID 31683923, 2019). "Interestingly, in 2013, it was recognized that a rare, non-heritable, aggressive form of retinoblastoma is actually driven by high-level MYCN amplification with normal RB1 genes." (PMID 31683923, 2019). "Unlike the human situation, mice heterozygous for Rb1 do not develop retinoblastoma." (PMID 27739525, 2016). "The hypothesis that the proliferative consequence of RB1 inactivation in the retina is age-dependent is underscored by the fact that retinoblastoma does not occur after the retina is fully developed." (PMID 27115612, 2016). "This reduction was associated with a significant inhibition in growth, which was reduced from 60 to 80% in WERI Rb1 and by about 50% in Y79, as found by CCK-8 assay, further supporting a role for ligand-driven Notch signaling in promoting retinoblastoma growth." (PMID 27661116, 2016). "In mice, inactivation of Rb1 is necessary but not sufficient for the development of retinoblastoma." (PMID 26275142, 2015). "In this context, it might be plausible for RB1-negative retinoblastoma cells to show constitutive activation of STAT3." (PMID 25359779, 2014). "Although the ocular tumors showed features of retinoblastoma tumors, the expression level of the rb1 tumor suppressor was unchanged in pretumor and elevated ∼3 fold in tumor tissue, indicating the tumors do not arise due to deletion of the rb1 locus." (PMID 25485542, 2014). "However, mouse chimeras bearing cells with Rb1 homozygous deletion also do not form retinoblastomas or osteosarcomas." (PMID 21403899, 2011). "Arguments against this notion are that mice do not develop retinoblastoma with MYCN over-expression unless they also have deficient Rb1 expression and that RB1 functions may be inactivated in the RB1-proficient, MYCNA retina by phosphorylation or by other means than gene mutation." (PMID 35729105, 2022). "Besides RB1 mutations, a small proportion of patients (1%) with retinoblastoma may have MYCN amplifications driving their disease, not an RB1 loss of function mutation." (PMID 32633890, 2020). "While loss-of-function RB1 mutations are universally detected in retinoblastoma and SCLC, RB1 is much more frequently inactivated in human tumors by p16 loss providing evidence that p16 also has critical tumor suppressive functions that are not mediated through RB1 in humans." (PMID 28414317, 2017). "Despite complete pRB inactivation, mice with disrupted RB1 genes do not spontaneously develop retinoblastoma like humans." (PMID 39000021, 2024). "Although we also found additional chromatin loop in HDF (human fibroblasts) control cells in intron 17 adjacent to exon 18 of the RB1 gene, but not in RB44 cells and retinoblastoma-specific RPE control cells, we thus focused on the E5-E7 looping." (PMID 36175480, 2022).